QKI (QKI, KH domain containing RNA binding)
Diseases named in the same sentence as QKI in open-access papers (continued):
Sharing a sentence is not in itself a finding about the gene and the disease.
breast carcinoma (continued). "Furthermore, biological function experiments showed that GAS5 suppressed breast cancer growth via IGF2BP2/QKI, and this inhibitory effect was modulated by FTO both in vitro and in vivo, thus representing a promising strategy for the treatment of breast cancer." (PMID 38782769, 2024). "GAS5 recruited IGF2BP2 to target QKI and upregulated QKI expression in breast cancer cells." (PMID 38782769, 2024). "QKI, a tumor suppressor that represses breast cancer, was predicted as a possible target of GAS5." (PMID 38782769, 2024). "To identify transcripts whose AS is likely to play a functional role in promoting EMT, we assessed which QKI and RBFOX1-regulated AS events were also associated with an EMT gene signature across a panel of breast cancer cell lines from the Cancer Cell Line Encyclopedia (CCLE)." (PMID 30059005, 2018). "Since mesenchymal and stem-like cell features are enriched in basal-like breast cancer, we examined whether the splicing of FLNB and the expression of QKI or RBFOX1 were associated with the basal-like subtype in TCGA Breast Invasive Carcinoma (BRCA) samples." (PMID 30059005, 2018). "Among all the common targets of QKI and RBFOX1, we found that CD44 (IC:0.857, p value:<6.59e-07) and FLNB (IC:0.848, p value:<6.59e-07) scored as the top two genes that most strongly associated with the EMT signature in breast cancer cell lines." (PMID 30059005, 2018). "Similarly, we discovered elevated expression of QKI (NM_006775, also called QKI-5) in basal-like breast cancers relative to other subtypes of breast cancers." (PMID 30059005, 2018). "In conclusion, GAS5 represses the growth of breast cancer through regulating the IGF2BP2/QKI pathway, and this inhibitory effect is modulated by FTO-mediated m6A modification, suggesting that the FTO/GAS5/IGF2BP2/QKI pathway may be a potential target for breast cancer treatment." (PMID 38782769, 2024). "Here, our observations indicated that QKI expression could be induced by stimulation with tamoxifen or estrogen deprivation, and thus, its downstream effect is likely to be involved in the modulation of tamoxifen sensitivity in breast cancer cells." (PMID 37524698, 2023). "Expression of SLUG and QKI was correlated with epithelial to mesenchymal transition (EMT), and showed promise for use in breast cancer prognosis." (PMID 41048341, 2025). "GAS5 regulated by FTO-mediated m6A modification represses the growth of breast cancer via the IGF2BP2/QKI pathway, suggesting that the FTO/GAS5/IGF2BP2/QKI pathway can be a potential target for breast cancer treatment." (PMID 38782769, 2024). "We found several targets of QKI and RBFOX1, including FLNB, SLK, USO1, ENAH, ESYT2, NUMB and ARHGEF1, to be among the most differentially spliced genes in basal B breast cancer cell lines." (PMID 30059005, 2018). "Here, we found that QKI and RBFOX1 regulate the splicing of an exon in the actin-binding protein FLNB to regulate the EMT in breast cancer." (PMID 30059005, 2018). "We also found that QKI expression was low in breast cancer tissues and positively correlated with GAS5 expression, suggesting that GAS5 may regulate QKI." (PMID 38782769, 2024). "In breast cancer, TPT1-AS1 and QKI share a binding site in miR-330-3p." (PMID 39479357, 2024). "While the levels of all QKI isoforms increase during EMT and are higher in mesenchymal compared with epithelial breast cancer cells, it is unclear whether QKI-6 and -7 play a role in the mesenchymal state." (PMID 38019605, 2024). "To determine whether the effects of QKI on APA occur more broadly, we examined expression of long and short 3’UTR isoforms of our candidate genes in breast cancer cell lines within the Cancer Cell Line Encyclopaedia." (PMID 38112323, 2024). "In addition, QKI and RBFOX1 overexpression also significantly increased the CD44-high cell populations in two additional breast cancer cell lines (MCF7 and ZR75-1)." (PMID 30059005, 2018).
breast carcinoma (continued). "To determine the extent of QKI autoregulation in the context of breast and prostate cancer EMT, we examined the effect of knockdown of QKI-5 in a mesenchymal prostate cancer cell line (PC-3), a mesenchymal breast cancer cell line (MDA-MB-231), and a mesenchymal breast cell line (mesHMLE)." (PMID 38019605, 2024). "Moreover, we found that circRNA-SFMBT2 biogenesis could be facilitated via RNA-binding protein quaking (QKI), and biologically elevated circRNA-SFMBT2 expression promoted cell growth and tamoxifen resistance in ER+ breast cancer." (PMID 37524698, 2023). "To assess whether the negative correlation holds at the protein level, we measured QKI protein in a panel of breast cancer cell lines, which showed an even stronger negative correlation with miR‐200c." (PMID 29871889, 2018).
glioma (21 papers, 2010 to 2025). A benign or malignant brain and spinal cord tumor that arises from glial cells (astrocytes, oligodendrocytes, ependymal cells). "The glioma risk factor RBP QKI drew our attention because multiple consensus QREs are found immediately upstream of the human NEAT1 PAS." (PMID 39032650, 2024). "Emerging evidence suggests dysregulation of AS in human disorders that involve deficiency of QKI, such as schizophrenia and glioma." (PMID 24792162, 2014). "In order to study the role of QKI in astrocytes, we used small interference RNA (siRNA) designed to suppress the expression of specific QKI splice variants in human astrocyte glioma cells, and studied the effect of silencing on global gene expression." (PMID 20927331, 2010). "Astrocyte glioma cells were treated with three different pools of siRNA designed to silence all QKI splice variants (QKI-tot), or only splice variant QKI-5 or QKI-7." (PMID 20927331, 2010). "Furthermore, we found that the RBP quaking (QKI), a glioma risk factor, regulates the biogenesis of NEAT1 isoforms through facilitating NEAT1 PAS usage in glioma cells." (PMID 39032650, 2024). "Alterations in the expression levels of specific QKI isoforms have also been associated with schizophrenia, major depression, anxiety, ataxia, and glioma, highlighting the importance of a better understanding of the diverse functions of QKI, particularly during nervous system development." (PMID 26727370, 2016). "This abundance of mRNA and miRNA targets accounts for the pleiotropic nature of mutations in QKI and its links to a wide range of human diseases, which include glioma, colon cancer, schizophrenia, major depressive disorder, 6q terminal deletion syndrome and ataxia." (PMID 23520467, 2013). "In order to figure out the oncogene associated with glioma, we selected five genes to preform qRT-PCR experiments, including XPR1, QKI, CREB5, ACVR2B and ABL2." (PMID 37407973, 2023). "Another pathophysiological process characterized by alterations in QKI is the development of gliomas." (PMID 32194626, 2020). "It will be important to evaluate the different QKI isoform abnormalities in glioma samples on a larger scale, and to elucidate their precise functions in tumorigenesis in future studies." (PMID 28212562, 2017). "In glioblastoma, QKI suppresses TGFβ signaling pathway by upregulating miR-20a, and impairs the stem cell functions of glioma stem cells." (PMID 29064439, 2017). "We studied the effect of small interference RNA (siRNA)-mediated QKI depletion on global gene expression in human astrocyte glioma cells." (PMID 20927331, 2010). "We identified QKI recognition element (QRE) sequences located upstream of the human NEAT1 PAS, which are consensus RNA motifs containing ACUAAY-(1–20 nt)-UAAY for the binding of the glial RBP QKI encoded by a glioma risk gene." (PMID 39032650, 2024). "Consequently, the QKI gene tends to be eliminated in gliomas, either through a complete deletion or through a disruption by translocation." (PMID 32194626, 2020). "QKI impairs the stem cell functions of glioma stem cells, and neural stem cells." (PMID 29064439, 2017). "In summary, we were able to efficiently silence QKI in astrocyte glioma cells." (PMID 20927331, 2010). "Angiocentric gliomas typically show alterations in the MYB gene, most often rearrangements with QKI as a partner, although other partners have been also described." (PMID 39422766, 2024). "Located in the 6q25-27 chromosomal region, PRKN is commonly lost/deleted in GBM similar as QKI, and PARKIN protein expression was shown to be downregulated during glioma progression." (PMID 36051438, 2022). "In this regard, the frequent deletion of the QKI locus found in GBMs may affect NEAT1 isoform biogenesis and glioma tumor development." (PMID 39032650, 2024).
glioma (continued). "The significance of QKI deregulation in brain tumors is further highlighted by the observation that 90% of angiocentric gliomas, a type of low-grade pediatric glioma, contain MYB-QKI fusions, which transform cells by concomitantly activating MYB and suppressing QKI." (PMID 35653194, 2022). "While the roles for upstream regulators of QKI, hsa-miR-208b-3p and hsa-miR-208a-3p, in glioma have not yet been described, another miRNA that affects schizophrenia risk, hsa-miR-494-5p, is a definite glioma suppressor." (PMID 32194626, 2020).
schizophrenia (21 papers, 2007 to 2024). A major psychotic disorder characterized by abnormalities in the perception or expression of reality. "Within the central nervous system, QKI has been associated with the onset and progression of numerous neuropsychiatric disorders, including schizophrenia, depression, ataxia, and Alzheimer’s disease." (PMID 39479357, 2024). "For example, miR-214 promotes dendritic development by targeting the schizophrenia-associated gene QKI, and miR-138 restricts the size of dendritic spines by regulating APT1." (PMID 36824367, 2023). "Another genetic study evaluated the mRNA expression of Quaking I (QKI), finding two splice variants to be downregulated in patients with schizophrenia." (PMID 32425837, 2020). "QKI was identified as a potential SZ gene because it is the only gene located in the chromosome susceptibility locus, 6q25-6q27, in a schizophrenia pedigree." (PMID 31019524, 2019). "For example, QKI is known to be involved in oligodendrocyte development and myelination as well as in inhibiting dendrite formation in the central nervous system, and mutations in QKI have been linked to ataxia and schizophrenia." (PMID 29116363, 2018). "At the post-transcriptional level, the selective RNA-binding protein QKI, a glia-specific risk factor of schizophrenia, binds FEZ1 mRNA." (PMID 29249816, 2017). "The QKI gene is implicated as being important in schizophrenia, and QKI controls the translation of many oligodendrocyte-related genes." (PMID 25971746, 2015). "Decreased expression of the glial gene Quaking (QKI), encoding an RNA binding essential for myelination, has been reported in schizophrenia brain." (PMID 22937264, 2011). "The human QKI gene, called quaking homolog, KH domain RNA binding (mouse), is a candidate gene for schizophrenia encoding an RNA-binding protein." (PMID 20927331, 2010). "An earlier study showed decreased expression levels of QKI splice variant seven (QKI-7) in frontal cortex of schizophrenia patients." (PMID 19335891, 2009). "A previous study showed that post-mortem samples from schizophrenia patients had different mRNA levels of QKI splice variants depending on the medication received by the patients." (PMID 19335891, 2009). "The association of QKI protein with human pathology suggests that in the central nervous system, QKI is involved in the onset of various neuropsychiatric disorders, including schizophrenia, depression, ataxia, and Alzheimer’s disease." (PMID 39479357, 2024). "QKI protein has been revealed in human and was associated with many human diseases, such as cancer, and neurological diseases, such as human hereditary ataxia, various sclerosis, or schizophrenia." (PMID 32952599, 2020). "In addition to the clusters of single-nucleotide polymorphisms in human QKI that co-segregate with schizophrenia, reduced QKI expression is observed in the postnatal brains of multiple schizophrenia cohorts." (PMID 29249816, 2017). "The same QKI splice variant was shown to be downregulated in patients with schizophrenia." (PMID 22937274, 2011). "Our results indicated that QKI regulates the mRNA levels of myelin and oligodendrocyte genes in the human brain, and that changes in the balance between QKI splice variants may be linked to altered myelination in schizophrenia." (PMID 17822540, 2007). "Therefore, the authors suggested that decreased activity of some myelin-related genes in schizophrenia may be caused by disturbed QKI splicing." (PMID 22937274, 2011). "The QKI gene contributes to a number of human diseases, including cancers, myelin disorders, and schizophrenia, and it is a critical regulator of alternative splicing in cardiac myofibrillogenesis and contractile function." (PMID 37521848, 2022). "This region contains only one gene described in the literature and the human databases, quaking homolog, KH domain RNA binding (mouse) (QKI), pointing to the potential involvement of QKI in schizophrenia." (PMID 22937274, 2011).
schizophrenia (continued). "Previous research efforts concentrated on the study of QKI function in oligodendrocytes because multiple lines of evidence implicate this cell type in schizophrenia." (PMID 20927331, 2010). "QKI has been proposed as a candidate gene for schizophrenia after several lines of evidence including linkage analysis and mRNA expression studies." (PMID 20927331, 2010). "Although decreased QKI expression in the brain of schizophrenia patients has been shown by several groups, the nature of the cells with reduced expression, and the physiological effect in the brain of patients is not known." (PMID 20927331, 2010). "The expression defects of QKI in schizophrenia might lead to selective splicing defects of several myelin genes." (PMID 39479357, 2024). "The alteration of QKI expression may result in myelin disorders, such as multiple sclerosis and schizophrenia." (PMID 34063504, 2021). "The quaking homolog, KH domain RNA binding (mouse) (QKI) is a candidate gene for schizophrenia." (PMID 19335891, 2009). "QKI controls expression of oligodendrocyte related (OR) genes, as reviewed previously, and expression of OR genes has clearly been shown to be altered in schizophrenia." (PMID 19335891, 2009). "Interestingly, GOMAFU can directly interact with the splicing factors quaking (QKI) and SRSF1 (serine/arginine-rich splicing factor 1), and when GOMAFU is dysregulated, the alternative splicing resembles that seen in schizophrenia-associated genes DISC1 and ERBB4." (PMID 31019524, 2019). "The lncRNA GOMAFU can change the AS events of schizophrenia-related genes DISC1 and ERBB4, and GOMAFU can interact with splicing factors QKI and SRSF1, which may be the mechanism of GOMAFU participating in the AS process." (PMID 34750493, 2022).
prostate carcinoma (16 papers, 2015 to 2026). A carcinoma that arises from epithelial cells of the prostate gland. "QKI expression was reduced in prostate cancer tissue and was associated with cell differentiation, the TNM stage and the overall survival rate." (PMID 32931453, 2020). "Studies have identified that high methylation of the QKI promoter is the reason for decreased QKI expression in colorectal cancer, stomach cancer, and prostate cancer." (PMID 39479357, 2024). "LncRNA MEG3 was reported to affect proliferation and migration of prostate cancer cells through regulating miR-9-5p/QKI-5 axis." (PMID 38824534, 2024). "A recent study demonstrated that the combined therapy of radiation (RT) and metformin suppresses the progression of prostate cancer (PCa) by modulating the QKI/circZEB1/miR-141-3p/ZEB1 signaling pathway, enhancing radiation sensitivity." (PMID 39479357, 2024). "Overexpression of QKI in castration-resistant tumors was also validated in another prostate cancer dataset." (PMID 36672609, 2022). "We also observed that QKI is overexpressed in castration-resistant prostate cancers due to repression of the miR-200 family." (PMID 36672609, 2022). "Accordingly, QKI overexpression inhibited prostate cancer cell proliferation and tumorigenesis in vitro and in vivo." (PMID 32931453, 2020). "QKI is a tumor suppressor in several cancers, including oral cancer, prostate cancer, colorectal cancer, gastric cancer, and brain cancer." (PMID 25971746, 2015). "QKI has been shown to be a tumor suppressor in brain tumors, colon cancers and prostate cancers." (PMID 30059005, 2018). "Suppression of QKI transcription was previously found in colon, gastric, and prostate cancers, suggesting that hsa_circ_0001445 expression might be regulated similarly via QKI in HCC." (PMID 29785229, 2018). "Consistent with its reciprocal relationship with miR‐200 and miR‐375 in cancer, QKI expression increased during TGF‐β‐induced EMT of human breast and canine kidney epithelial cells and during ZEB1‐induced EMT of LNCaP human prostate cancer cells." (PMID 29871889, 2018). "Among protein nodes, QKI, YOD1, and TBL1XR1 were the most connected, with 19, 15, and 14 edges, respectively (which ranks potential biomarkers and their impacts in prostate cancer)." (PMID 41598250, 2026). "To determine whether QKI autoregulation of 3’UTR length occurs in other contexts, we generated a second series of cell lines with the same QKI manipulations in the prostate cancer cell line PC-3." (PMID 38112323, 2024). "(b) Distribution of transcript levels of splicing regulators DDX5, DDX17 and QKI, assessed by RT-qPCR and normalized to GUSB, in androgen positive and negative prostate cancer cell lines." (PMID 31164793, 2019).